METTL14 (methyltransferase 14, N6-adenosine-methyltransferase non-catalytic subunit)
Diseases named in the same sentence as METTL14 in open-access papers (continued):
Sharing a sentence is not in itself a finding about the gene and the disease.
tumor (continued). "On the contrary, METTL14, ZC3H13, FTO, and WTAP are low-expressed in tumor tissues." (PMID 32258108, 2020). "Importantly, knock-down of both METTL14 and EBNA3C together led to the most dramatic decrease in tumor weight and volume." (PMID 31226160, 2019). "Our work defined Mettl14 as a tumor suppressor gene in bladder and a negative modulator in bladder TICs." (PMID 31760940, 2019). "The downregulation of METTL14 acts as a poor prognostic indicator for survival without recurrence in HCC and has a close association with tumor metastasis." (PMID 30062093, 2018). "Likewise, when we transplanted PBT726 cells with KD of METTL3 or METTL14 into the brains of NSG mice, we observed a substantial increase in tumor growth compared to that in mice transplanted with control cells." (PMID 28297667, 2017). "In addition, downregulation of METTL14 reduced m6A modification of C/EBP homologous protein (CHOP) mRNA and decreased CHOP protein levels, and low CHOP levels reduced the apoptosis-inducing effect of REGO on tumor cells, increasing tumor resistance to REGO." (PMID 40356985, 2025). "Additionally, overexpression of METTL14 has been shown to increase the translation efficiency of MN1 mRNA, leading to all-trans retinoic acid (ATRA) chemotherapy resistance and accelerating tumor progression." (PMID 39897026, 2025). "METTL14 is a noncatalytic subunit of the N6-adenosine-methyltransferase complex which can regulate mRNA function and stabilize mRNA transcripts to accelerate tumor progression." (PMID 38355626, 2024). "The expression of the regulators significantly varies based on tumor stage in a few cancers, including KIRP, KIRC, KICH, LIHC, OV, THCA, and TGCT; IGF2BP2 in KIRC and THCA; IGF2BP3 in KIRP, KIRC, and UCEC; and LRPPRC and METTL14 in KIRC are the ones that are the most varied." (PMID 39457524, 2024). "Decreased expression of seven m6A regulators [METTL14, YTHDC2, FTO, ALKBH5, HNRNPA2B1, VIRMA, and RNA-binding motif protein, X chromosome (RBMX)] was evident in OC tissues sample and in the advanced-stage cohort, suggesting crucial roles in tumor suppressors of OC progression." (PMID 38544837, 2024). "Additionally, a subcutaneous tumor model in nude mice demonstrated that loss of METTL3 significantly inhibited the tumorigenic ability of EC109 cells, while loss of METTL14 did not significantly affect tumor growth." (PMID 38965238, 2024). "Although METTL3 and METTL14 could inhibit the proliferation of tumor cells, we did not observe the effect of METTL3 and METTL14 knockdown on cell proliferation." (PMID 36819040, 2023). "By comparing the expression of m6A related gene in the tumor group and the normal group (METTL14, YTHDF2 and YTHDF3 could not be excluded with statistical significance), mutation rates of m6A gene were all greater than 0, which could not be excluded." (PMID 37194014, 2023). "Consistently, our results showed that circSTX6 expression was regulated by METTL14 in an m6A‐dependent manner and such regulation also existed in HCC tumour and adjacent normal tissues, which extended our knowledge of m6A‐modified circRNAs in tumour progression." (PMID 37877357, 2023). "Additionally, METTL14-mediated m6A modification maintains sirtuin 6 (SIRT6) stability by regulating the expression of ubiquitin-specific peptidase 48 (USP48) and promoting the tumor suppressive function of glycolysis to regulate the metabolic activity of HCC." (PMID 36120301, 2022).
tumor (continued). "Therefore, the expression levels of 7 m6A regulators (METTL14, YTHDC2, FTO, ALKBH5, HNRNPA2B1, VIRMA, and RBMX) were lower in both the OC tissues and the high-stage group, indicating their potential function as tumor suppressors in OC tumorigenesis and development." (PMID 34631700, 2021). "Moreover, we demonstrated that METTL14 overexpression could suppress PTC cell proliferation, migration/invasion, and OIP5-AS1 overexpression alleviated METTL14-mediated effects on PTC tumor progression." (PMID 34131102, 2021). "However, other factors such as sex, age, tumor location, tumor size, macroscopic type, and histologic grade were not related to METTL14 expression." (PMID 33314339, 2021). "Hence, our study highlights the significant role of METTL14 and OIP5-AS1 in PTC tumor progression." (PMID 34131102, 2021). "Furthermore, the downregulation of METTL14 is closely related to malignant progression and poor recurrence-free survival (RFS) and overall survival (OS) of patients, suggesting the potential role of METTL14 in predicting tumor metastasis and recurrence." (PMID 32443966, 2020). "Co-expression analysis revealed that METTL14 and ZC3H13 had a strong positive correlation with APC, an antagonist of the Wnt signaling pathway, indicating they might cooperate in regulating proliferation, invasion, and metastasis of tumor cells." (PMID 33363011, 2020). "However, unlike AML, METTL3 and METTL14 serve as tumor suppressors to inhibit GBM stem cell self-renewal and tumor progression." (PMID 32111216, 2020). "Interestingly, METTL14 seems to exert negative influences on tumor glucose metabolism." (PMID 38531882, 2024). "A lack of METTL14 in macrophages can also inhibit the antitumor function of CD8+ T cells and promote tumor growth." (PMID 39199429, 2024). "Research has confirmed that only intervening with METTL14, rather than METTL3, can reduce the level of m6A methylation modification in tumour cells." (PMID 38263865, 2024). "The analysis indicated that, in comparison to the Normal group, the Tumor group's expression of METTL3 was considerably up-regulated, that of FTO was down-regulated, and those of METTL14 and ALKBH5 were not significantly affected." (PMID 37828232, 2023). "In the present study, our analysis suggests that expression levels of the ‘writers’ METTL3 and METTL14 and the ‘reader’ YTHDC1 are involved in HPV-dependent VSCC tumorigenesis, but not HPV-independent tumor development." (PMID 36050747, 2022). "METTL3, METTL14, WTAP and CBLL1 were expressed at the protein level in both non-malignant prostate and tumour tissue." (PMID 36733939, 2022). "Nevertheless, using the TCGA and CPTAC tumor dataset, we did not observe substantial genetic alterations or upregulations of METTL3 and METTL14 in cancer." (PMID 34285249, 2021). "As well, reduced level of the m6A members METTL3, METTL14, WTAP and FTO but not their mutation and overexpression was tightly associated with cancer progression and poor survival, and these could be developed as novel prognostic markers to predict tumor recurrence." (PMID 30953473, 2019). "However, in our study, both at the cellular level and in tumor tissues, METTL3 did not exhibit cytoplasmic localization, suggesting that the METTL3-independent function from METTL14 occurs within the nucleus, at least under our experimental conditions." (PMID 38965238, 2024). "Notably, there is a negative correlation between METTL3/METTL14 and STAT1 in tumor tissues of 59 patients." (PMID 35693795, 2022). "However, also in U2OS and HeLa tumor cells, we found no recruitment of METTL3 and METTL14 enzymes at the DNA lesions." (PMID 32033081, 2020).
cancer (258 papers, 2017 to 2026). A tumor composed of atypical neoplastic, often pleomorphic cells that invade other tissues. "For the METTL family, two METTL14 cancer-associated mutations (R298P and D312Y) are located near the METTL3–METTL14 interaction interface." (PMID 38429855, 2024). "A cancer-associated mutant of METTL14, R298P, targets the heterodimer to both canonical 5ʹ-AC-3ʹ methylation sites and aberrant 5ʹ-AU-3ʹ methylation sites, altering the m6A methylation profile and target gene expression." (PMID 38429855, 2024). "Crystal structure data, for example, have provided insight into cancer-associated mutations in METTL14." (PMID 36894952, 2023). "The decreased expression of METTL14 was strongly associated with metastasis of cancer to lymph nodes and other body parts, as well as the TNM stage of cancer." (PMID 37915034, 2023). "Since miR‐375 targeted YAP1, a proliferation‐associated protein, METTL14 eventually repressed cancer cell proliferation in CRC." (PMID 36162823, 2023). "Recently, m6A modification mediated by METTL14 has been implicated in the occurrence and development of tumors, and METTL14 plays a role in promoting cancer." (PMID 37805597, 2023). "Therein, METTL14, as one of N6-methyladenosine (m6A) related genes, has been found to be associated with promoting tumorigenesis in different cancers." (PMID 33430867, 2021). "In clear cell renal cell carcinoma (ccRCC), METTL3 and METTL14 constitute a risk signature for use in prognostics, because they are significantly enriched in cancer-related pathways, including the Wnt/β-catenin signaling pathway." (PMID 34315512, 2021). "METTL14, as one of N6-methyladenosine (m6A) related genes, has been found to be associated with promoting tumorigenesis in different types of cancers." (PMID 33430867, 2021). "METTL14 is now a new target for development of therapeutics for treatment of EBV-associated cancers." (PMID 31226160, 2019). "Our study elucidates the link between nucleotide metabolism and RNA epigenetics in tumorigenesis through the PRPS2-MAT2A-WTAP/METTL3/METTL14 axis, providing potential insights for drug design and discovery in cancers associated with PRPS2 abnormalities, such as lung adenocarcinoma." (PMID 40295500, 2025). "In addition to METTL3, METTL14 has also been shown to enhance tumorigenesis and be associated with poor prognosis in several types of cancers." (PMID 39006762, 2024). "Recent studies of METTL3 and METTL14 in cancers have shown that they are closely associated with the processes involved in the proliferation, apoptosis, metastasis, and differentiation in the progression of various human cancers." (PMID 35455436, 2022). "A mutation in METTL14 could promote cancer cell proliferation through decreasing m6A level and activating AKT signaling pathway." (PMID 32710725, 2020). "Interestingly, METTL14 was found to be positively associated with cancer prognosis in several other scenarios." (PMID 33584787, 2020). "METTL14, another m6A writer protein, has also been linked to cancer development." (PMID 30149601, 2018). "Moreover, a cancer-associated mutation in METTL14 not only decreased methyltransferase activity but also decreased the substrate specificity of the MTC, such that both the consensus sequence GGACU and the non-consensus sequence GGAUU were methylated at similar efficiencies." (PMID 33159022, 2020). "Curdione, as a drug, was found to promote ferroptosis in cancer cells by up regulating the expression of METTL14 and YTHDF2, which in turn affected the expression levels of SLC7A11, SLC3A2, HOXA13 and GPX4180." (PMID 41522342, 2026).
cancer (continued). "Studies have underscored m6A dysregulation, particularly aberrations in METTL3 and METTL14 levels, across various cancers, including breast, colorectal, liver, and lung cancers." (PMID 40785027, 2025). "Collectively, while METTL14 represents a promising target in cancer immunotherapy, future studies should carefully consider its context-dependent functions, mechanistic complexity, and translational constraints to fully realize its therapeutic potential." (PMID 41164187, 2025). "Dysregulation of m6A machinery, including methyltransferases (METTL3, METTL14), demethylases (FTO, ALKBH5), and m6A readers (YTHDFs, IGF2BPs), has been implicated in oncogenesis, immune evasion, and therapy failure in multiple cancers, including HNSCC." (PMID 41624157, 2025). "Collectively, our results provide strong evidence that METTL14 serves as a key regulator in linking inflammation and cancer." (PMID 41316520, 2025). "To elucidate the reason for the diminished m6A levels in GBC, we evaluated the expression of key m6A regulatory factors (METTL3 and METTL14) in paired cancer and normal tissue samples." (PMID 40785027, 2025). "In ESCC cells, METTL14 promotes pri-miR-99a maturation and miR-99a-5p stability, enhancing stemness in cancer cells and increasing radioresistance." (PMID 40823093, 2025). "Other small molecule inhibitors that target METTL3/METTL14 were tested in different cancer cell lines." (PMID 40483535, 2025). "The PRMT1 inhibitor MS023 effectively inhibits METTL14 methylation and markedly reduces its capacity to promote cancer cell proliferation and clonogenicity, suggesting that PRMT1 is pivotal in carcinogenesis through the regulation of METTL14's PTM." (PMID 41256732, 2025). "Our findings are in strong agreement with existing literature and highlight the emerging role of METTL14 in linking inflammation and cancer, although this role requires further investigation." (PMID 41316520, 2025). "By inhibiting this pathway via m6A modification, METTL14 indirectly suppresses cancer cell migration and invasion." (PMID 39802639, 2025). "Given m6A's oncogenic roles in many cancers, the development of inhibitors targeting m6A writers, including METTL14, has garnered substantial interest for cancer therapy, leading to remarkable progress." (PMID 39936533, 2025). "METTL14 enhances the stem cell-like properties of cancer cells by promoting the maturation of pri-miR-99a and stabilizing miR-99a-5p, thereby conferring radioresistance to ESCC cells." (PMID 40823093, 2025). "Preclinical studies have demonstrated that pharmacological inhibition of METTL14 reduces global m6A levels, destabilizes oncogenic transcripts, and suppresses malignant tumor progression." (PMID 41164187, 2025). "Our study links nucleotide biosynthesis with RNA epigenetics in cancer progression through the PRPS2-MAT2A-WTAP/METTL3/METTL14 axis, and elucidates both enzyme-dependent and independent functions of PRPS2." (PMID 40295500, 2025). "METTL14-mediated m6A methylation affects the expression of numerous genes, thereby influencing cancer cell behavior." (PMID 40746896, 2025). "METTL14, as one of the main members of m6A writers, plays an important role in the mechanisms related to malignant tumors." (PMID 41256854, 2025). "Given the broad oncogenic roles of METTL3 in cancers, it is very interesting that METTL14 exerts antitumor functions in an m6A-depnedent manner in most tumors, which brings our attention to understand their roles as a whole MTC." (PMID 40734692, 2025). "While METTL14 plays a crucial role in cancer, its regulation of immune‐ and inflammation‐related genes remains poorly understood." (PMID 41316520, 2025).
cancer (continued). "As exploration on m6A modification deepens, more and more evidence suggests that METTL14 plays an important role in various cancer types." (PMID 41323393, 2025). "In nasopharyngeal carcinoma, METTL14 promotes cancer progression by regulating the stability of AOC1 mRNA." (PMID 41256854, 2025). "METTL14 is upregulated in gemcitabine‐resistant cancer cells which increases the expression of gemcitabine metabolizing enzyme cytidine deaminase (CDA)." (PMID 39661414, 2024). "Our results indicated that Regorafenib exerts effects on cell cycle arrest in cancer cells through the regulation of CHOP via the METTL14-m6A pathway." (PMID 38664644, 2024). "We discovered that FAM110B expression often showed a favorable correlation with pan-cancer gene expression associated with m1A, m5C, and m6A, particularly in YTHDF3, YTHDC1, NSUN3, TET2, and METTL14." (PMID 39170745, 2024). "In certain circumstances, restoration of METTL3 and METTL14 expression to re‐establish m6A distribution can inhibit cancer cell progression." (PMID 39006762, 2024). "Our data has shown that down-regulating of METTL14 efficiently impaired cancer cell growth and metastasis in vivo and in vitro." (PMID 39138186, 2024). "Most studies have shown that METTL14 can play a role in cancer inhibition, but some studies have also confirmed that METTL14 can promote tumorigenesis and development." (PMID 39289775, 2024). "Recent studies have revealed that METTL14 acts as an oncogene or a suppressor in diverse human cancers." (PMID 39831202, 2024). "METTL14 enhanced m6A methylation on the seven in absentia homolog 2 (Siah2) ubiquitin ligase which is responsible for proteasomal degradation of PD‐L1 in cancer cells." (PMID 39661414, 2024). "Specific PROTACs induced significant degradation of METTL3 and METTL14 across multiple cancer cell lines, demonstrating a new approach to modulate epitranscriptomic proteins in cancer therapy." (PMID 39377984, 2024). "Recent studies have uncovered the crucial role of DGCR8 in pri‐miRNA processing and how it often necessitates METTL3 or METTL14 in different cancer types." (PMID 38380598, 2024). "Changes in FTO and METTL14 levels largely affect the in vitro proliferation, migration, and invasion of cancer cells." (PMID 38491196, 2024). "Often working together, the METTL3/METTL14 complex plays an oncogenic role in various cancers, including breast, kidney, and liver cancer, but has an anti-cancer effect in neuroblastoma." (PMID 39155349, 2024). "On the other hand, METTL14, which is the methyltransferase of m6A mRNA, has several functions in cancer cells, such as regulating leukemogenesis and proliferation of hematopoietic stem/progenitor cells (HSPCs)." (PMID 38491196, 2024). "In this study, we found that the m6A level in the NSCLC tissues was higher, and the expression of METTL14 was also up-regulated in the NSCLC tissues compared to the para-carcinoma tissues." (PMID 38326804, 2024). "It is noteworthy that the dysregulation of METTL3 and METTL14, and consequently m6A methylation, can have a significant impact on cancer progression." (PMID 38148841, 2023). "Like METTL3, METTL14 can also affect miRNA maturation in an m6A-dependent manner to promote or suppress cancer progression." (PMID 37437245, 2023). "The representative m6A methyltransferases and demethylases, such as ALKBH5, METTL3, and METTL14, have been widely studied in cancer development." (PMID 37647025, 2023). "Previous studies have shown that Methyltransferase-like 14 (METTL14) is involved in the tumorigenesis of various malignant tumors." (PMID 36941564, 2023). "Mechanically, we demonstrated that METTL14 inhibited cancer stem cell characteristic by regulating β-catenin." (PMID 37283789, 2023). "Regulated by a histone deacetylase 2-mediated epigenetic mechanism, the METTL14-miR-99a-5p-tribble 2 positive feedback loop promotes radiotherapy resistance and cancer stem cell persistence in ESCC." (PMID 37744275, 2023).